AADACL4 (arylacetamide deacetylase like 4)
Synonyms: OTTHUMG00000001889
Tractability: Antibody: UniProt predicts a signal peptide or a membrane-spanning region.
Gene: Protein-coding gene on chromosome 1 (12,644,085 to 12,667,076, forward strand). Ensembl gene ENSG00000204518.
Subcellular location: Membrane
Gene Ontology:
Molecular function: carboxylic ester hydrolase activity; hydrolase activity
Cellular component: membrane
Genetic constraint (gnomAD): Loss-of-function variants: 9 observed, 14.78 expected, observed/expected ratio (o/e) 0.61, 90% interval 0.37 to 1.06. The upper end of that interval is the gene's LOEUF score, 1.06, which puts it in group 4 of 6, group 1 being the genes least tolerant of losing a copy. Missense variants: 531 observed, 542.7 expected, observed/expected ratio (o/e) 0.98, 90% interval 0.91 to 1.05. Synonymous variants: 188 observed, 213.36 expected, observed/expected ratio (o/e) 0.88, 90% interval 0.78 to 0.99.
Homologues: Orthologues: chimpanzee AADACL4 (99% identical), macaque AADACL4 (95% identical), pig AADACL4 (71% identical), rat AAdacl4fm3 (66% identical), rat AAdacl4fm3l1 (66% identical), mouse Aadacl4 (65% identical), mouse Aadacl4fm4 (64% identical), mouse AAdacl4fm3 (64% identical), rat Aadacl4 (64% identical), mouse Aadacl4fm1 (61% identical), rat Aadacl4fm1 (59% identical), mouse Aadacl4fm5 (59% identical), and 4 more. Paralogues in human: AADACL3 (55% identical), AADAC (30% identical), NCEH1 (30% identical), AADACL2 (29% identical), AFMID (14% identical).
Diseases named in the same sentence as AADACL4 in open-access papers:
AADACL4 is named in the same sentence as 2 diseases in open-access papers, as found by Europe PMC text mining. Sharing a sentence is not in itself a finding about the gene and the disease. The quoted sentences say what the papers report.
acute kidney injury (1 paper, 2025). Sudden and sustained deterioration of the kidney function characterized by decreased glomerular filtration rate, increased serum creatinine or oliguria. "Genes AADACL4 and RERGL, both suppressed by acute kidney injury (AKI) and ABMR, were increased at week 52, also suggesting recovery from injury." (PMID 40301559, 2025).
AADACL4 also shares sentences with these, for which no sentence is quoted: uterine sarcoma (1 paper).